SMAD4 (SMAD family member 4)
Diseases named in the same sentence as SMAD4 in open-access papers (continued):
Sharing a sentence is not in itself a finding about the gene and the disease.
cancer (continued). "Previous studies have demonstrated that the decreased expression levels of TβRI, SMAD3 and SMAD4 may cause cancer cells to escape the growth inhibition of TGF-β1, and the increased expression of SMAD7 may block the inhibitory effects of TGF-β1." (PMID 25295107, 2014). "In HNSCC, reduced SMAD4 expression was associated with more aggressive cancer phenotypes." (PMID 23826135, 2013). "A loss of Smad4 expression is a common finding in many cancers." (PMID 22335355, 2012). "Consequently, mutation analyses in many cancers have highlighted the MH2 domain of SMAD4 as a mutational hotspot." (PMID 21835029, 2011). "Our results reveal a diametrically opposed role for Smad4 inactivation in sustaining liver and lung metastases and establish a critical interplay between driver mutations and organ-biased chromatin states that contributes to the heterogeneity of cancers driven by identical genetic lesions." (PMID 40999053, 2025). "In conclusion, this study supports the potential of RNA analyses in the clinical classification of SMAD4 splicing variants in order to ensure tailored genetic counseling, management, and surveillance for patients with a suspected genetic predisposition to GI polyposis and/or cancer." (PMID 39063183, 2024). "Thus, low SMAD4 expression is linked to unfavorable outcomes in several types of cancers." (PMID 38003265, 2023). "Thus, Smad4 deficiency plays a crucial role in cancer development." (PMID 38129938, 2023). "Moreover, we cannot conclude that loss of SMAD4 expression could be potentially used as a molecular marker for cancer resistance in clinical therapy when we use animal xenograft models." (PMID 34048444, 2021). "The loss of SMAD4 expression could affect the progression and treatment of cancers." (PMID 33117720, 2020). "In comparison, the strongest candidate cancer driver identified among the miRNA biogenesis genes was SMAD4." (PMID 40867048, 2025). "SMAD4, a well-known tumor suppressor gene frequently lost in many cancers, including OSCC, plays a pivotal role in several key signaling pathways, such as the TGF-β, BMP, and WNT pathways." (PMID 40338154, 2025). "Blocking polymorphonuclear MDSCs effectively inhibits cancer progression in Pten/Smad4 mouse models." (PMID 40007149, 2025). "The analysis of the CDS mutations using OncodriveFML revealed a very strong and distinct signal for SMAD4 as a potential cancer driver (q < 0.1)." (PMID 40867048, 2025). "Based on these findings, we confirmed that BI sup induces cancer cell death through the upregulation of SMAD4/TGF-beta." (PMID 39113194, 2024). "One of the downstream proteins of β-catenin is SMAD4, which is overexpressed in various types of cancer." (PMID 38205087, 2024). "Similar to this study, Smad4 silencing in epithelial cells promoted the expression of CCL20, thereby enabling susceptibility to colitis-associated cancer." (PMID 39346534, 2024).
cancer (continued). "All these findings reveal the important role of the SMAD4 gene in various cancers and suggest that its potential similar role in the development of CRC should be explored." (PMID 39164192, 2024). "In this study, we expanded the landscape of SMAD4 splicing variants acting as causative events in JPS etiology and cancer." (PMID 39063183, 2024). "A total of 75 index cases with CPs and a personal/family history of cancer were analyzed to identify genetic alterations in major hereditary polyposis-associated genes (APC, BMPR1A, MUTYH, PTEN, SMAD4, STK11)." (PMID 39518056, 2024). "Patients with DPC4-expressed cancers exhibit longer survival, emphasizing the significance of SMAD4 in treatment outcomes." (PMID 38666907, 2024). "Zfra-activated Hyal-2+ CD3- CD19- Z cells in the spleen, via Hyal-2/WWOX/Smad4 signaling, are potent in cancer suppression." (PMID 38542478, 2024). "Although constitutive phosphorylation of SMAD4 has been observed in epithelial and cancer cells, the site of phosphorylation of SMAD4 remains to be identified." (PMID 38543112, 2024). "A cohort study involving 28 cancer patients has revealed that individuals with reduced expression of Smad4 exhibit a higher overall chemotherapy response." (PMID 39440050, 2024). "For example, TGFβ–BMP signalling was mostly inactivated by co-SMAD SMAD4 mutations in MSS cancers, but by one or more indel receptor mutations (TGFBR2, ACVR2A, BMPR2 and ACVR1B) in MSI cancers." (PMID 39112709, 2024). "In the present study, early-stage CRC significantly downregulates the tumor suppressor genes Apc and Smad4, reflecting their pivotal roles in cancer suppressive pathways." (PMID 38674816, 2024). "Both peptides probably mediate the signaling from membrane Hyal-2/WWOX and then recruit Smad4 for blocking cancer growth." (PMID 38542478, 2024). "While ID1 was the most significantly upregulated in SMAD4-expressing tumors, it is a well-known target of BMP4 and has been implicated in the promotion of metastasis in different cancer types." (PMID 38689334, 2024). "An analysis with Reactome showed significant enrichment of SMAD2/3 and SMAD4 MH2 Domain Mutants in Cancer (p-value < 0.01)." (PMID 39484215, 2024). "Using RNA-seq and qRT‒PCR analysis, we confirmed that BI sup upregulates SMAD4, thereby inducing cancer cell death." (PMID 39113194, 2024). "In conclusion, our study demonstrates that the anti-metastatic effect of BMP4 is mediated by SMAD4-dependent signalling that is transduced either in the cancer cells or in the stromal cells." (PMID 38689334, 2024). "In lung cancer, Tranilast inhibits TGF-β1-induced EMT and cell invasion by suppressing Smad4 expression, leading to reduced pleural dissemination of cancer cells." (PMID 39534084, 2024). "SMAD4 markedly diminishes the rate of extracellular acidification and elevates the rate of oxygen consumption in cancer cells." (PMID 38686046, 2024). "The implication of SMAD4 in ferroptosis suggests a nuanced role in cancer cell survival and death, offering potential therapeutic avenues to exploit this vulnerability in SMAD4-positive cancers." (PMID 38975339, 2024). "This compound reactivates dormant SMAD4R361H-mediated transcriptional activity and restores TGF-β-induced tumor suppression in SMAD4 mutant cancer cells." (PMID 39727835, 2024). "Next, we performed a literature review of SMAD4 splicing variants to explore the association between genetic alterations that affect SMAD4 splicing and the JPS clinical phenotype and cancer susceptibility." (PMID 39063183, 2024). "Monoubiquitylation also regulates the SMAD4-mediated signaling, and it is worth mentioning that SCFskp2 E3 ligase ubiquitylates SMAD4 at the MH2 domain, enabling SMAD4 mutations in cancer to be degraded." (PMID 38543112, 2024).
cancer (continued). "SMAD4/TGF-beta has been studied for its role in suppressing cancer by disrupting EMT function in cancer cells." (PMID 39113194, 2024). "In this study, we found that the increase in SMAD4/TGF-beta levels induced by B. infantis DS1685 supernatant (BI sup) in cancer cells disrupted regulation of the EMT mechanism." (PMID 39113194, 2024). "The Hyal-2/WWOX/Smad4 signaling induces spleen Hyal-2+ CD3- CD19- Z cell activation for eradicating cancer cells." (PMID 38542478, 2024). "A gene-phenotype association in terms of cancer risk in JPS has been identified, with cancer being less frequently observed in BMPR1a DCV carriers than SMAD4 DCV carriers (8.5% vs 20.5%)." (PMID 37400896, 2023). "Given MYC and SMAD4 are known to be modulated by statins, the phenotypic switch caused by high and low doses of the same uPAR modulator may become an interesting research topic to elucidate whether these cancer driver genes could also serve as surrogate markers in anti-cancer therapies." (PMID 37895906, 2023). "The TGF-β/SMAD4 signaling pathway controls a wide range of cellular processes including proliferation, differentiation, apoptosis, migration, and cancer initiation and progression." (PMID 36900240, 2023). "In another study by Blatter and colleagues, incidence of cancer was also higher in SMAD4 carriers, with 20.5% of patients with GI cancer (26/127), compared to 8.4% (8/94) in BMPR1A carriers (p = 0.015)." (PMID 38066625, 2023). "To this end, we used a human CRC organoid model that faithfullyreflects the cancer progression effects of SMAD4 inactivation in advancedCRC." (PMID 36450103, 2023). "Elevated levels of SMAD4 or CD8 + cytotoxic T cells are associated with a longer life span, whereas increased CD15 + neutrophil level indicates decreased survival in various cancers." (PMID 37035326, 2023). "Together, these data clearly show that TGF signaling was protective against cancer progression, as also indicated by data on the role of SMAD4 in CRC." (PMID 37190048, 2023). "An increasing number of studies have detected a correlation between SMAD4 and survival for many kinds of cancer." (PMID 37478236, 2023). "Myocardin and SMAD3/SMAD4 form a positive feedback loop that drives TGF-β-induced EMT in NSCLC cancers." (PMID 37685308, 2023). "Instead, T-cell-specific co-Smad4 deletion led to spontaneous development of cancer with increased Th17 cell differentiation, suggesting that Smad4 has functions beyond promoting TGF-β signaling in T cells." (PMID 37217798, 2023). "In a study by Aytac and colleagues, following regular surveillance and appropriate polypectomies, 4/27 individuals with SMAD4 DCVs developed cancer, in comparison to 0/8 of BMPR1A + JPS patients." (PMID 38066625, 2023). "Recent studies have indicated that inactivation of SMAD4 is related to disease progression in various cancers." (PMID 38003265, 2023).
cancer (continued). "We showed that the restoration of a functional Smad4 in SMAD4-defective cancer cells restored TGFβ signaling and decreased cell proliferation in vitro, particularly in 3D, and in proportion to their SMAD4 expression level." (PMID 37377893, 2023). "Consistent with previous reports, we also showed that the restoration of SMAD4 expression in SMAD4-defective cancer cells decreased in vivo tumorigenesis." (PMID 37377893, 2023). "We herein provide evidence of a SMAD2/3 oncogenic effect in response to TGF-β1 in SMAD4-null human PDAC cancer cells." (PMID 36207615, 2022). "Serum cancer antigens CA125 and CA19-9 were positively associated with SMAD4 alterations while high CEA was enriched in wild-type CDKN2A subgroup." (PMID 35180847, 2022). "These promoters and alternative transcripts they generate remain unexplored as contributors to the SMAD4 deregulation in cancer." (PMID 35034624, 2022). "Research demonstrated that SMAD4-mediated binding to the Rorc locus promotes the differentiation and maturation of Th17 lymphocytes, which exacerbate cancer migration and metastatic spreading." (PMID 35887766, 2022). "On the other hand, sequence analysis revealed a homozygous expression of SMAD4 P130L in EpCAM+ cancer cells, but it failed for other EpCAM-negative fractions." (PMID 36293034, 2022). "Agonist Zfra4-10 or WWOX7-21 peptide, HYAL-2 antibody or sonicated hyaluronan HAson8, also activate the HYAL-2/WWOX/SMAD4 signaling for spleen Z cell activation in order to kill cancer cells in vitro and in vivo." (PMID 35883580, 2022). "This suggested that compared to the SMAD4 wild-type cancer cells, the culture condition favors more the growth of cancer cells with SMAD4 deletion." (PMID 35484598, 2022). "Though SMAD2 and 3 are rarely mutated in cancers, SMAD4 is lost in about 50% of PDAC, and the role of SMAD2/3 in a SMAD4-null context remains understudied." (PMID 36207615, 2022). "As a result, the SMAD4 protein expression level was relatively higher in the MIA-PaCa-2 model than in other PDAC cancer cell line models, and PAI-1 protein increased in the 3 mg/kg group at 72 h after h4#147D administration." (PMID 36385956, 2022). "At the residual cancer in the resected specimen, SMAD4 was highly expressed after NAC-RT (P = 0.039)." (PMID 36088360, 2022). "Although the functional consequences of reduced SMAD4 protein levels in SINET are unclear, SMAD4 mutations in other types of cancers shift signaling by TGFβ from growth inhibiting to cancer promoting." (PMID 33509126, 2021). "Taken together, these results provide evidence that inhibitor of miR‐378 suppresses cancer cell proliferation, migration, invasion, and angiogenesis through Smad4." (PMID 33372356, 2021).
cancer (continued). "Further, a great number of studies indicate that activation of Smad4 contributes to cancer development and progression." (PMID 33372356, 2021). "The function and significance of positive or negative regulators of SMAD4 are being studied in many cancers." (PMID 34070531, 2021). "These markers have been known as renal CSC marker in previous studies; therefore, we suggest that SMAD4 inhibition reduces the stemness properties of cancer cells." (PMID 34012911, 2021). "The canonical TGF-β/SMAD4 signaling pathway has been demonstrated to be a tumor suppresser in many cancer types including GC." (PMID 34743754, 2021). "We further found that the expression of Smad4 in NSCLC was lower than that in normal lung tissue adjacent to cancer and that Smad4 was downregulated or deleted in poorly differentiated, lymph node metastatic, and later clinical stage NSCLC." (PMID 33794845, 2021). "The TGF-β/SMAD4 signaling pathway has a crosstalk with many other pathways and is famous in a plenty area, including cancer, EMT, microRNA, DNA damage response and DNA damage repair." (PMID 34743754, 2021). "Binding of β-TrCP and SMAD4 was noted to be enhanced in LINC00941-silenced cancer cells but conversely, LINC00941 overexpression significantly inhibited the binding of β-TrCP and SMAD4." (PMID 33511320, 2021). "In this section, we will discuss how SMAD4 strategically worked with oncogenic LncRNAs to promote cancer." (PMID 33511320, 2021). "miR-34a overexpression significantly inhibited bone metastasis, whereas overexpression of SMAD4 not only increased the invasion of cancer cells to the bones and but also accelerated bone damage." (PMID 33511320, 2021). "TGF-β hinders the activity of ANT2 in cancer cells by establishing an NF1/Smad4 complex, and this suppression of ANT2 promotes senescence-associated oxidative stress, as well as DNA damage." (PMID 34947978, 2021). "It will be important in the future to understand in the cancer context, to what extent TGF-β family signaling is still functional in tumors harboring SMAD4 mutations and deletions." (PMID 34737283, 2021). "The most frequently mutated genes were TNRC6A, DICER1, SMAD4 and ZCCHC11, with mutations in 2–3% of pan-cancer samples." (PMID 33406242, 2021). "Relevant studies detecting SMAD4 expression in cancer patients treated with chemo-drugs up till December 2020 were systematically searched in four common scientific databases using selected keywords." (PMID 34048444, 2021). "SMAD4 has a key role in the tumorigenesis of many human cancers, including prostate, colorectal, and gastric cancers and its dysregulation has also been found in few types of cancers." (PMID 34012911, 2021). "Smad4 protein in the malignant tissues from advanced stages was also significantly lower than the early cancer stages (p < 0.05)." (PMID 34867090, 2021). "Mutations in the WNT (e.g. APC or CTNNB), EGFR (e.g. KRAS, PIK3C or BRAF) and TGF-β (e.g. SMAD4) signalling pathways gradually render cells independent from niche signals to grow autonomously and promoting cancer." (PMID 33594337, 2021). "SMAD4 has been found to be inactivated to varying degrees in many types of cancer; the purpose of this study was to investigate the correlation between SMAD4 expression in non-small cell lung cancer (NSCLC) and clinical pathological parameters." (PMID 33794845, 2021).